TRPV4 (transient receptor potential cation channel subfamily V member 4)
Diseases named in the same sentence as TRPV4 in open-access papers (continued):
Sharing a sentence is not in itself a finding about the gene and the disease.
Hypertension (continued). "In hypertension, the potential importance of TRPV4 to vascular control is increased since the physical forces that act on the endothelium (such as shear stress and intravascular pressure) are substantially altered." (PMID 39440451, 2025). "Yet the relationship between Ca2+ entry via TRPV4 channels and the vascular changes that accompany hypertension is disputed." (PMID 39440451, 2025). "The sustained Ca2+ signals occurring at high levels of TRPV4 activation in hypertension appear to elicit contraction as a result of reduced endothelium-dependent relaxation." (PMID 39440451, 2025). "For example, previous studies have shown that improving impaired endothelial TRPV4‐KCa2.3 coupling can protect against the progression of hypertension." (PMID 39744893, 2025). "In hypertension, there is increased expression of TRPV4 and, significantly, a decreased expression of IP3 receptors." (PMID 39440451, 2025). "The question arises as to why different types of contractile responses occur to the Ca2+ signaling events evoked by TRPV4 activation in hypertension." (PMID 39440451, 2025). "It is the increased expression of TRPV4 and decreased expression of IP3 receptors that predisposes the artery to sustained Ca2+ rises and contractions that occur at high levels of TRPV4 activation in hypertension." (PMID 39440451, 2025). "Hypertension increased endothelial TRPV4 expression compared to control rats, while SMC showed a low level of TRPV4 expression." (PMID 40366385, 2025). "To examine TRPV4-mediated regulation of blood vessel diameter in hypertension, we assessed vascular reactivity in small mesenteric arteries." (PMID 39440451, 2025). "Yet, despite their acknowledged importance to endothelial Ca2+ influx, published studies present a complicated picture of the role of endothelial TRPV4 channels in hypertension." (PMID 39440451, 2025). "In hypertension, TRPV4 activation generated increased vasodilator responses at low levels of channel activation." (PMID 39440451, 2025). "In support, in a nitric oxide synthase inhibitor-induced model of hypertension, blood pressure was greater in global TRPV4 knockout than in control normotensive mice." (PMID 39440451, 2025). "Our results show there is a notable shift in vascular reactivity in hypertension characterized by enhanced endothelium-dependent vasodilation at low levels of TRPV4 channel activation." (PMID 39440451, 2025). "We investigated the involvement of TRPV4 channels in the vascular changes occurring in a genetic model of hypertension (SHR)." (PMID 39440451, 2025). "We next investigated the possibility that the hypertension-induced alterations in TRPV4 function and signaling were paralleled by changes in the endothelial cell transcriptome." (PMID 39440451, 2025). "In hypertension, TRPV4-mediated control of vascular function is disrupted, but the underlying mechanisms and precise physiological consequences remain controversial." (PMID 39440451, 2025). "Similar results were observed in obesity-induced hypertension, suggesting that TRPV4 channel activity contributes to increased tone, elevated blood pressure, and medial thickening during hypertension." (PMID 39731196, 2024). "In the vascular system, TRPV4 expression is widely reported in vascular smooth muscle cells (VSMCs), and TRPV4 plays an important role in the regulation of blood pressure and the development of hypertension." (PMID 38256251, 2024). "In AngII-induced hypertension mice, the molecular coupling between TRPV4 channels and eNOS in aortic ECs is reduced, resulting in decreased NO production." (PMID 39731196, 2024). "In patients with hypertension and in mouse models of hypertension, VSMCs showed elevated TRPV4 activity, resulting in signal amplification for the simulation of α1 adrenergic receptor." (PMID 38256251, 2024). "The TRPV4/α1AR signaling axis was elevated in hypertension, whereas the TRPV4/BK complex was decreased, highlighting a potential new therapeutic target for hypertension." (PMID 36091375, 2022).
Hypertension (continued). "High concentrations of lactic acid can aggravate renal fibrosis conditions via activating TRPV4-TGFβ1-SMAD2/3-CTGF-mediated renal fibrotic pathways in spontaneous hypertension." (PMID 36160854, 2022). "An earlier study of mice with AngII-induced hypertension likewise showed impairment of ACh- and TRPV4 agonist-induced vasorelaxation mechanisms in the mesenteric arteries." (PMID 34616307, 2021). "Emerging evidence suggests that the dysregulation of endothelial TRPV4 channels underpins endothelial dysfunction associated with cardiovascular disease (CVD) risk factors, including hypertension, obesity, diabetes, and aging." (PMID 34616307, 2021). "In parenchymal arterioles of mice with angiotensin II (AngII)-induced hypertension, the reduced expression and function of both TRPV4 and SKCa underpin impaired carbachol- and TRPV4 agonist-induced (probably EDH-mediated) vasorelaxation." (PMID 34616307, 2021). "An increasing number of studies on hypertension have focused on the Ca2+ and TRPV-4 pathways in recent years." (PMID 35370628, 2021). "Regarding the TRPV4’s role in hypertension, it was mainly related to its vasodilatory actions through the endothelium." (PMID 32854408, 2020). "The downregulation of endothelial TRPV4 seems to be secondary to hypertension because the function and expression of TRPV4 were preserved in pre-hypertensive SHRSP." (PMID 29361737, 2018). "Our data highlight the importance of impaired TRPV4‐KCa2.3 interaction in the progression of hypertension and provide a novel strategy for developing new antihypertensive drugs with fewer adverse effects." (PMID 28899928, 2017). "Together, our data highlight the importance of impaired endothelial TRPV4‐KCa2.3 coupling in the progression of hypertension and suggest a novel approach for antihypertensive drug development." (PMID 28899928, 2017). "Murine hypertension models, induced by high‐salt diet, N(G)‐nitro‐l‐arginine intake, or angiotensin II delivery, showed decreased TRPV4‐KCa2.3 interaction in ECs." (PMID 28899928, 2017). "We show there is increased TRPV4 expression and TRPV4-mediated Ca2+ signaling in hypertension." (PMID 39440451, 2025). "In the present study, it seems likely that TRPV4 suppresses relaxation at higher levels of activation in hypertension (rather than cause contraction) because TRPV4 activation did not cause contraction by itself in an artery that was not preconstricted." (PMID 39440451, 2025). "Thus, aberrant ang II/TRPV4/eNOS pathway in endothelial cells is likely involved in the development of hypertension." (PMID 40028160, 2025). "Similarly, small molecules have been developed to restore decreased TRPV4–eNOS interaction and treat hypertension." (PMID 39744893, 2025). "Our study was undertaken to examine endothelial TRPV4-mediated Ca2+ responses in hypertension." (PMID 39440451, 2025). "However, at higher levels of TRPV4 activity, this vasodilatory response is reversed, contributing to the aberrant vascular tone observed in hypertension." (PMID 39440451, 2025). "The consequences of increased TRPV4-mediated Ca2+ signaling in hypertension are complex." (PMID 39440451, 2025). "The function of endothelial TRPV4 in hypertension is bidirectional." (PMID 40366385, 2025). "Low levels of TRPV4 activity may offer some protection, while at higher levels of activity, TRPV4 may contribute to the increased vascular tone that accompanies hypertension." (PMID 39440451, 2025). "For example, in hypertension, TRPV4 expression may be reduced and, as a result, channel activity impaired." (PMID 39440451, 2025). "Moreover, impaired TRPV4–eNOS interaction in aortic arteries is identified as a significant factor in hypertension progression." (PMID 39744893, 2025). "However, in various studies, the changes in TRPV4 activity have been reported as being both protective and a contributor to the pathological changes that occur in hypertension." (PMID 39440451, 2025).
Hypertension (continued). "High levels of TRPV4 activity may occur in hypertension as a result of the increased mechanical stimuli generated by increased pressure and flow velocity in small vessels, which may contribute to the vascular changes underlying hypertension." (PMID 39440451, 2025). "TRPV4 expression and distribution are substantially increased in hypertension." (PMID 39440451, 2025). "Strikingly, VSMC-specific Trpv4-knockout mice were protected from hypertension." (PMID 38256251, 2024). "The yellow cluster included terms related to vascular dysfunction and inflammation, such as “hypertension,” “blood pressure,” “endothelium,” “TRPV4,” and “inflammation,” which may indicate that TRPV4 is associated with vascular dysfunction and inflammation." (PMID 36910533, 2023). "Similarly, Diaz and co-authors showed that angiotensin II-induced hypertension results in TRPV4 mediated astrocytic [Ca2+]i changes and subsequent changes in perivascular arterial blood flow." (PMID 37108263, 2023). "Of particular interest is that both endothelial SKCa and TRPV4 channels seem to be compromised during hypertension because these two channels are preferentially localized in caveolae, which are specialized lipid rafts on which a number of transduction proteins are located." (PMID 29361737, 2018). "One possible explanation is that the upregulation of TRPV4 may be a compensatory mechanism to maintain endothelial function in salt-induced hypertension." (PMID 29361737, 2018). "This possibility and in-depth mechanisms underlying the effects of cinnamic acid against ang II-mediated hypertension, for instance, whether TRPV4 and/or whether direct vasodilatory effects of cinnamic acid on endothelial cells is involved, are to be investigated in the future." (PMID 40028160, 2025). "The observed increase in TRPV4-mediated relaxation and the biphasic response to TRPV4 activation in arteries from SHR animals (initial relaxation followed by a reversal to contraction at higher concentrations) suggest a complex regulatory mechanism involving TRPV4 in hypertension." (PMID 39440451, 2025). "Notably, TRPV4-mediated dilation in mouse pial arteries is impaired in the mouse model of AD; likewise, TRPV4 is shown to be fundamental in parenchymal arteriolar dilation and cognitive function in hypertension." (PMID 37020858, 2023). "Thus, they concluded that TRPV4 channel-mediated signalling could be targeted in order to reduce vasoconstriction and lower blood pressure in hypertension." (PMID 37238629, 2023). "Thus, the combined actions of both Piezo1 and TRPV4 may contribute to the endothelial vascular barrier dysfunction in hypertension." (PMID 33298523, 2021). "The issue of whether or not the loss of endothelial SKCa and TRPV4 channels during hypertension is associated with any changes in caveolae warrants further investigation." (PMID 29361737, 2018). "Our findings also reveal that while the sensitivity of endothelial cell TRPV4 to activation was unchanged, expression of the channel is upregulated and IP3 receptors are downregulated in hypertension." (PMID 39440451, 2025). "At the myoendothelial junction of AngII-induced hypertension mice, AKAP150 expression is attenuated, and ACh-induced EDHF generation by the TRPV4/AKAP150/PKC complex is reduced." (PMID 39731196, 2024). "The polymodal cation channel TRPV4 has been suggested to set the hypotensive phase of the circadian IOP clock and induce hypertension in response to mechanical stress." (PMID 39041037, 2024). "However, in the process of hypertension, the expression of TRPV4 and SK protein in the endothelium was significantly reduced, and the impairment of the TRPV4-eNOS pathway may reveal that endothelium TRPV4 participates in the pathophysiological changes in hypertension." (PMID 38255767, 2024). "In hypertension, at lower levels of TRPV4 activity, there is increased dilation when compared with normotensive controls." (PMID 39440451, 2025).
Hypertension (continued). "These include the following: TRPV4 may potentially serve no substantial role in the blood pressure changes, may act as a compensatory mechanism to offset elevations in blood pressure, or may be a cause that underlies the increased blood pressure that characterizes hypertension." (PMID 39440451, 2025). "The reason for the discrepancy between the two studies with respect to the expression of TRPV4 during hypertension is not known." (PMID 29361737, 2018). "Although limited information is currently available about the role of TRP channels in altered EDH-mediated responses during hypertension, several recent studies shed light on the endothelial TRP vanilloid type 4 (TRPV4) channels as a potential target for this alteration." (PMID 29361737, 2018). "In VSMCs from hypertensive patients and AngII-induced hypertension models, the TRPV4/AKAP150/α1AR/PKC molecular complex was increased, enhancing the contribution of TRPV4 channels to vasoconstriction, whereas the TRPV4/RyR/BKCa channel molecular complex was decreased." (PMID 39731196, 2024). "We have examined the effect of high glucose on TRPV4 and SGK1 expression in an attempt to better elucidate the role of these regulatory proteins in maintaining cell volume under physical stress and thus preventing the development of secondary hypertension which is often observed in DN." (PMID 23049542, 2012).
neuropathy (30 papers, 2015 to 2026). A disorder affecting the nervous system that manifests with pain, tingling, numbness, and/or muscle weakness. "Variants in TRPV4 have been associated with two major disease groups: skeletal dysplasias and neuropathies, with recent findings indicating an overlap in their clinical features." (PMID 41097048, 2025). "When a TRPV4 inhibitor is introduced, it promotes neurite growth in both wild-type TRPV4 and neuropathy-causing mutants." (PMID 39333347, 2025). "Regarding TRPV4, which is usually activated by heat and mechanical stimuli, it has been implicated in taxane-induced neuropathy; indeed, TRPV4 antagonists or knock-out mice attenuate pain and nerve injury." (PMID 38672107, 2024). "We then analyze its interaction with RhoA to elucidate the mechanism of TRPV4 inhibition by RhoA, as well as the impact of human neuropathy mutations on TRPV4 gating." (PMID 37353484, 2023). "Strikingly, most residues mutated in TRPV4-mediated neuropathy (R237, R269, R315, and R316) are clustered at the interface with RhoA." (PMID 37353484, 2023). "We previously showed that neuropathy-causing mutations (R232C, R237L, R269C, R315W) in TRPV4 disrupt the interaction with RhoA, consistent with our structures." (PMID 37353484, 2023). "We and others have previously shown that neuropathy-causing mutations in TRPV4 result in increased basal and stimulated channel activity." (PMID 35300980, 2022). "We also confirmed NEDD4-mediated suppression of neuropathy mutant channel activity by examining a second neuropathy-causing mutant (R237L TRPV4) in MN-1 cells." (PMID 35300980, 2022). "We further demonstrate that neuropathy-causing mutations in TRPV4 reduce channel ubiquitination correlating with increased channel activity, but enhancing ubiquitination of neuropathy mutants dampens their responses to agonist stimulation." (PMID 35300980, 2022). "A potential clue to tissue specificity in TRPV4 disease comes from the observation that neuropathy mutations most frequently occur at highly conserved, surface-exposed arginine residues within the ARD17." (PMID 33664271, 2021). "Neuropathy-causing mutations of TRPV4 disrupt this complex, leading to RhoA activation and impairment of neurite extension in cultured cells and flies." (PMID 33664271, 2021). "Remarkably, all tested neuropathy mutations resulted in nearly complete disruption of TRPV4–RhoA interaction, whereas the skeletal dysplasia mutations displayed variably preserved interaction with RhoA." (PMID 33664271, 2021). "Given that neuropathy mutations within the convex face of the N-terminal ARD of TRPV4 disrupt RhoA interaction, we examined the interaction of RhoA with the TRPV4 N terminus." (PMID 33664271, 2021). "Together, these data suggest that TRPV4–RhoA interactions modulate TRPV4 channel activity, and that this modulatory effect is disrupted by neuropathy-causing mutations." (PMID 33664271, 2021). "Together, these results suggest that neuropathy mutant TRPV4 can cause cytoskeletal disruption in vivo through excessive activation of RhoA, and these defects can be rescued by RhoA inhibition." (PMID 33664271, 2021). "All variants reported were heterozygous and only one paper described a familial case of complex phenotype with severe intellectual disability and neuropathy associated with compound heterozygosity for TRPV4 mutations." (PMID 32641076, 2020). "Dominant missense mutations in TRPV4 cause a spectrum of in vivo neuropathies that can present congenitally or late in adulthood." (PMID 32471994, 2020). "Mutations in the TRPV4 gene are the cause of a spectrum of inherited diseases (or TRPV4-pathies), which include skeletal dysplasias, arthropathies, and neuropathies." (PMID 32443528, 2020). "Some studies suggest that neuropathy-causing mutations lead to a gain of TRPV4 ion channel function, whereas others argue they cause a loss of function." (PMID 32471994, 2020).